KRT81 (keratin 81)
Description:
Structural component of intermediate filaments in the hair cortex. Forms obligate heterodimers with type I hair keratins, which assemble into keratin intermediate filaments that contribute to the structural integrity and mechanical strength of the hair shaft.
Synonyms: K81; KRTHB1; MLN137; Hb-1; HB1; MNLIX2; ghHkb1; hHAKB2-1
Tractability: PROTAC: UniProt records ubiquitination sites on it; ubiquitination databases record sites on it.
Target class: Structural protein
Gene: Protein-coding gene on chromosome 12 (52,285,913 to 52,291,534, reverse strand). Ensembl gene ENSG00000205426.
Pathways (Reactome):
Developmental Biology: Formation of the cornified envelope; Keratinization
Gene Ontology:
Molecular function: protein binding; structural constituent of skin epidermis
Biological process: intermediate filament organization; keratinization
Cellular component: extracellular region; cytosol; keratin filament
Genetic constraint (gnomAD): Loss-of-function variants: 34 observed, 31.14 expected, observed/expected ratio (o/e) 1.09, 90% interval 0.83 to 1.45. The upper end of that interval is the gene's LOEUF score, 1.45, which puts it in group 6 of 6, group 1 being the genes least tolerant of losing a copy. Missense variants: 482 observed, 480.18 expected, observed/expected ratio (o/e) 1, 90% interval 0.93 to 1.08. Synonymous variants: 226 observed, 204.86 expected, observed/expected ratio (o/e) 1.1, 90% interval 0.99 to 1.23.
Homologues: Orthologues: macaque KRT81 (98% identical), chimpanzee KRT81 (96% identical), dog KRT81 (91% identical). Paralogues in human: KRT83 (93% identical), KRT86 (90% identical), KRT85 (80% identical), KRT84 (61% identical), KRT82 (58% identical), KRT5 (51% identical), KRT6A (50% identical), KRT6C (50% identical), KRT6B (50% identical), KRT75 (49% identical), KRT3 (48% identical), KRT76 (47% identical), and 56 more.